TFPI2 (tissue factor pathway inhibitor 2)
Diseases named in the same sentence as TFPI2 in open-access papers (continued):
Sharing a sentence is not in itself a finding about the gene and the disease.
cancer (72 papers, 2005 to 2026). A tumor composed of atypical neoplastic, often pleomorphic cells that invade other tissues. "The inclusion of TFPI2 as an insured cancer diagnostic marker in Japan has spurred heightened research interest." (PMID 40361374, 2025). "TFPI2 (Tissue Factor Pathway inhibitor 2) encodes a member of the serine proteinase inhibitor family, which plays a multifaceted role in regulating protease activity, tissue remodeling, and cancer progression." (PMID 40422184, 2025). "Overall, there is scant data in the literature on the effect of TFPI-2 gene mutations on cancer development." (PMID 39153052, 2024). "Researchers have observed that a loss of TFPI2 expression in many malignancies can antagonise the development and progression of cancers." (PMID 35501390, 2022). "Downregulation of TFPI2 is present in various types of cancer and is associated with malignant tumor progression; moreover, methylation of TFPI2 can predict the prognosis and metastasis of malignancy." (PMID 34249699, 2021). "There are several studies on the biological roles of TFPI2, a Kunitz-type serine proteinase inhibitor, associated with protecting the extracellular matrix of cancer cells from degradation." (PMID 33946400, 2021). "Aberrant methylation has been suggested as a possible mechanism for loss of TFPI-2 expression in several human cancers." (PMID 24695110, 2014). "Nevertheless our data show that LCT13 acts as an antisense RNA linked to TFPI-2 downregulation indicating that L1-derived transcripts can affect gene expression patterns in cancer by multiple mechanisms." (PMID 23703216, 2013). "TFPI2 has been identified as a tumor suppressor gene in several types of cancer, and is a diagnostic marker for clear cell type OC; however, our results suggest that it could be a prognostic marker for HGSC." (PMID 40422184, 2025). "Low TFPI-2 expression levels have been linked to cancer progression, recurrence and poor survival." (PMID 39153052, 2024). "The results may point to a new potential cancer gene therapy based on recombinant adeno-associated viral vector (rAAV) mediated TFPI-2 re-expression." (PMID 39153052, 2024). "Thus, down-regulation of miR-23a expression by HPV in cancer cells caused TFPI-2 expression to be silenced by promoter methylation." (PMID 39153052, 2024). "It is still unclear whether TFPI2 is associated with increased risk of development of VTE in other types of cancer as well." (PMID 37238908, 2023). "The modulation of clotting factor expression by ATRA may underlie the discrepancy effects of TFPI2 on cancer cell invasion." (PMID 29757260, 2018). "The loss of TFPI2 function might enhance the invasive potential of neoplastic cells in several cancers." (PMID 29137404, 2017). "Similarly, several studies indicate that aberrant methylation of TFPI-2 gene promoter is found to be associated with a variety of malignant tumors." (PMID 23497249, 2013). "Moreover, decreased expression of TFPI-2 associated with hypermethylation of the gene promoter was found in eight out of 10 patients with advanced stage of cancer (III or IV) compared to only one out of seven with stage I or II NSCLC (P=0.02)." (PMID 15685245, 2005). "Hence, the proteolytic inactivation of TFPI-2 by trypsinogen 4 might represent an additional “Loss of Function” mechanism favoring cancer by increasing angiogenesis." (PMID 26318044, 2015). "This study uncovers a promising therapeutic strategy for a broader subset of patients with GBM with high expression of either CLOCK or TFPI2, and provides a framework for identifying 'symbiotic exclusivity' genes in cancer." (PMID 41842961, 2026). "Some cancer tissues exhibit heterogeneous TFPI2 staining, with more differentiated tumors showing stronger expression." (PMID 40361374, 2025). "The epigenetic regulation of TFPI2 is anticipated to be an increasingly prominent focus in future cancer research." (PMID 40361374, 2025).
cancer (continued). "Analogous to cancer, TFPI2 expression in inflammatory settings is shaped by the surrounding microenvironment and is tightly regulated by immune and inflammatory signals." (PMID 40361374, 2025). "This bidirectional regulation suggests TFPI2 both responds to and modulates NF-κB, impacting inflammation and cancer." (PMID 40361374, 2025). "Since thrombin formation leads to activation of platelets, TFPI-2 indirectly down-regulates platelet aggregation and activation and thus lowers its ability to support cancer development." (PMID 39153052, 2024). "TFPI-2 functions as a potent inhibitor of plasmin and down-regulates plasmin-mediated proteolysis of ECM; consequently, up-regulation of TFPI-2 counteracts the ECM degradation by cancer cells." (PMID 39153052, 2024). "Functional assays have shown that TWIST1 reversed the inhibitory effects of over-expressed TFPI-2 on cancer." (PMID 39153052, 2024). "With this in mind, we provide an updated overview of the effects of TFPI-2, a protease inhibitor, on cancer development and metastasis." (PMID 39153052, 2024). "Nonetheless, the role of TFPI-2, which expression appears to be elevated in several other cancers such as CCC of the ovary and HCC, is incompletely understood." (PMID 39153052, 2024). "In human cancers, expression of TFPI-2 appears to be upregulated only in clear cell carcinoma (CCC) tissues." (PMID 39153052, 2024). "Decreased expression of TFPI-2 by aberrant methylation in the promoter region has been proposed as a mechanism contributing to cancer progression and recurrence, and to poor survival in BC patients." (PMID 39153052, 2024). "The results showed that compared to the normal tissue surrounding cancer, CYP24A1 and TFPI2 were significantly decreased in BC cancer tissue." (PMID 39068476, 2024). "Therapeutic attempts to restore or upregulate TFPI-2 expression in cancer are still in the early stages and further systematic studies are required." (PMID 39153052, 2024). "TFPI2 has been reported to inhibit migration, invasion, cell viability, and proliferation in many cancer cells." (PMID 37349838, 2023). "TFPI2, a tumor suppressor gene, has been shown to be upregulated in other cancers, including colorectal, gastric, and prostate." (PMID 35456486, 2022). "These three proteins (CA125, MK, and TFPI-2) were overexpressed in the cancer samples for all institutions, but the magnitude of overexpression varied between institutions." (PMID 35804849, 2022). "TFPI2 belongs to the Kunitz-type serine proteinase inhibitor family, and methylation of TFPI2 was found to be closely related to elevated cancer growth, invasion and dissemination." (PMID 36358701, 2022). "Although the methylation levels of ELMO1, ZNF582 and TFPI2 all showed a significant difference between each cancer type and control subjects, they still showed a preference for a certain cancer type." (PMID 36358701, 2022). "Higher expression of SERPINF1 and TFPI2 was accompanied by lower cancer stemness while with a higher stromal score, immune score and ESTIMATE score." (PMID 36505458, 2022). "Intriguingly, TFPI2 shares a common protease target, plasmin activity, with SerpinB2, and the latter promotes the survival of brain vascular coopting cancer cells." (PMID 34249699, 2021). "TFPI-2 has also been demonstrated to stimulate apoptosis in GBM cancer cells and to inhibit angiogenesis in experimental models." (PMID 33947134, 2021). "In tissue sample testing, the 2−ΔΔCt value showed a tendency of normal < cancer (p < 0.001) for either SDC2 or TFPI2." (PMID 35004840, 2021). "TFPI2 (tissue factor pathway inhibitor-2) is a Kunitz-type serine proteinase inhibitor that protects the extracellular matrix of cancer cells from degradation and inhibits in vitro colony formation and proliferation." (PMID 35004840, 2021).
cancer (continued). "The multifunctional DDS also showed folate-targeted codelivery of docetaxel (DOC) and tissue factor pathway inhibitor 2 TFPI2, which made cancer cells more sensitive to DOC and enhanced the antitumor effect compared with monochemotherapy." (PMID 33501883, 2021). "Due to downregulation of miR-23a expression by HPV in cancer cells, TFPI2 was silenced by promoter methylation." (PMID 32559232, 2020). "Hypermethylation, generally associated with decreased gene expression, was detected for TFPI2 in multiple types of cancer compared to normal adjacent tissues." (PMID 33381488, 2020). "The cumulative values in monocultures were higher than the measured values in co-cultures indicating a decrease of TFPI-2 expression in fibroblasts in the presence of cancer cells." (PMID 32559232, 2020). "Using linear regression models adjusted for age, urinary osmolality, and urinary leukocytes, we identified associations between B-As and four putative cancer-related proteins: FASLG, SEZ6L, LYPD3, and TFPI2." (PMID 33381488, 2020). "Using multiplex proteomic methods in urine samples, we identified four putative cancer-related proteins (FASLG, SEZ6L, LYPD3, and TFPI2) associated with arsenic exposure in women living around Lake Poopó, Bolivia." (PMID 33381488, 2020). "Promoter methylation of TFPI2 is detected in most of tumors (over 90% tested cancer patients samples) with OSCC and other cancer types as well which explained TFPI2 methylation can be useful for early detection biomarker rather than prognostic biomarkers." (PMID 31405379, 2019). "Bisulfite sequencing analysis confirmed the cancer-specific methylation of the TFPI2, SOX17, and GATA4 promoters in the OSCC cell lines and tumors but not in the normal oral mucosa samples." (PMID 31405379, 2019). "Methylated TFPI2 has been identified as a potential cancer biomarker with particular relevance to the early detection of cancer." (PMID 29084829, 2018). "Expression of TFPI-2 upon 5-aza treatment, a gene known to be induced in cancer cells upon this treatment, confirmed its effectiveness." (PMID 28300471, 2017). "Our data mining of the public databases discovered there was an inverse correlation between TFPI2 methylation and gene expression in different cancers." (PMID 29137404, 2017). "Ectopic expression of TFPI-2 protein in these cancer cell lines negatively regulates colony formation and inhibits cell proliferation." (PMID 21062455, 2010). "Transcriptional silencing by promoter hypermethylation of TFPI-2 was observed in some human cancers." (PMID 21062455, 2010). "Accordingly, expression of TFPI-2 immunoreactive protein in lysates of two normal and five cancer cell lines was analyzed by immunoblotting using an anti-TFPI-2 polyclonal antibody raised against recombinant human α-TFPI-2." (PMID 17352822, 2007). "Nevertheless, the mechanisms that alter/modify the expression of TFPI-2 gene in cancer cells are not well understood." (PMID 18053161, 2007). "It had also been reported that DNMT inhibitor restored expression of TFPI-2 in several cancer cell lines." (PMID 18053161, 2007). "The TFPI-2 gene has been mapped on chromosome 7q22, and deletions of the 7q region have been described in several malignant tumours, but this chromosomal abnormality is not a frequent feature of NSCLC." (PMID 15685245, 2005). "TFPI2 knockout enhances cancer proliferation and invasion via integrin α1/β1 clustering." (PMID 40361374, 2025). "Furthermore, the relationship between TFPI2 expression and prognosis in these cancers requires further investigation." (PMID 40361374, 2025). "Despite the lack of a definitive consensus regarding the physiological function of TFPI2, its pathophysiological significance has garnered increasing attention due to the substantial differences in blood TFPI2 concentrations between cancer patients and healthy individuals." (PMID 40361374, 2025). "Nuclear TFPI2 influences cancer-related gene expression and intracellular signaling." (PMID 40361374, 2025).
cancer (continued). "This review focuses on the role of TFPI-2 in cancer biology." (PMID 39153052, 2024). "Similarly, in urothelial cancer, the TFPI-2 level was found to be inversely correlated with increasing grade and stage of cancer." (PMID 39153052, 2024). "On the other hand, TFPI-2 was found to be up-regulated when melanoma-associated antigen 3 (MAGEA3) was silenced leading to impaired VM, with the implication that the influence of TFPI-2 on VM in different cancers requires further investigation." (PMID 39153052, 2024). "However, the exact role of TFPI-2 in cancer progression and possible approaches to up-regulate TFPI-2 expression warrant further studies." (PMID 39153052, 2024). "There have been attempts to modify the amount of TFPI-2 expressed in various cell types and cancer." (PMID 39153052, 2024). "TFPI-2 interacts with the thrombin cascade and also employs other mechanisms to suppress cancer growth and dissemination, which include extracellular matrix stabilization, promotion of caspase-mediated cell apoptosis, inhibition of angiogenesis and transduction of intracellular signals." (PMID 39153052, 2024). "Finally, tissue factor pathway inhibitor 2 (TFPI2) has been shown to promote cancer metastasis through increased perivascular migration and ERK signaling." (PMID 36980717, 2023). "Furthermore, in addition to its role in the coagulation and fibrinolysis system, TFPI1 and TFPI2 have also been found to regulate the proliferation, invasion, differentiation, and apoptosis of cancer cells and trophoblast cells." (PMID 37238908, 2023). "Moreover, aberrant methylation of the TFPI2 gene is significant in the decrease of TFPI2 expression in human cancers in general." (PMID 35571032, 2022). "TFPI2 could enhance the detection sensitivity of SDC2 especially for cancer in the left colon, rectum, and sigmoid colon." (PMID 35004840, 2021). "Moreover, tumors methylated for TFPI2 are often represent a more advanced stage in cancer development." (PMID 32559232, 2020). "Thus, we suggest that inhibition of TFPI-2 production in TFs further increases the aggressivity of cancer." (PMID 32559232, 2020). "Thus, reversing hypermethylation of TFPI2 at early stage of cancer, probably an efficient pathway to inhibit tumorigenesis." (PMID 30651599, 2019). "TFPI-2 was considered as a tumor suppressor gene in several types of cancer, including GB41." (PMID 30442884, 2018). "In addition, although TFPI2 hypermethylation has been reported in many human cancers, there existed some highlights in our study." (PMID 29137404, 2017). "Among these genes, HMGA2, CLDN1, TFPI2, KIAA0101 and EGR1 are cancer related genes according to Diseases Association Analysis and increased expression of EGR1 was confirmed by further semi-quantitative RT-PCR, quantitative RT-PCR and western blot in BCL6B re-expressed HepG2 and SNU449 cells." (PMID 25909168, 2015). "This is consistent with data available from the ENCODE project that also shows differences in the levels of the heterochromatic mark H3K27me3 between normal cells (HMEC), which are devoid of this mark and MCF-7 cancer cells that display H3K27me3 enrichment at TFPI-2." (PMID 23703216, 2013). "Conversely, TFPI-2 mRNA levels fall with increasing malignancy in the case of breast, gastric, colon, pancreatic, laryngeal, renal, endometrial, glial and several other human malignant tumors." (PMID 17352822, 2007). "However, direct evidence of TFPI2 activating PPARγ specifically in cancer cells remains limited." (PMID 40361374, 2025). "TFPI2 expression is also subject to epigenetic regulation, including DNA methylation and histone modifications, which may serve as clinically relevant biomarkers for cancer diagnosis, prognostication, and individualized therapy (right)." (PMID 40361374, 2025).
cancer (continued). "The peritumoral benign mucosa of cancer patients showed relatively high frequencies and levels of death-associated protein kinase (DAPK), O6-methylguanine DNMT (MGMT), and tissue factor pathway inhibitor-2 (TFPI2) methylation compared to normal mucosa from healthy volunteers." (PMID 38464391, 2024). "The same study indicated that TFPI-2 may have a pro-apoptotic role and be negatively related to the proliferative index (Ki-67), which is an indicator of the aggressiveness of bladder and other cancers." (PMID 39153052, 2024). "Furthermore, pyrosequencing confirmed the methylation of TFPI2 gene in cancer cells." (PMID 32559232, 2020). "As a consequence of promoter methylation, neither the TFPI2 mRNA nor the protein could be detected in T and C. Surprisingly, in spite of the fact that cancer-associated fibroblasts also failed to produce TFPI-2 protein, they remained unmethylated." (PMID 32559232, 2020). "Therefore, the restoration of TFPI2 expression suppresses the invasiveness of malignant tumors." (PMID 29757260, 2018). "In addition, we asked whether TFPI2 is involved in retinoid-induced suppression of cancer cell invasion." (PMID 29757260, 2018). "Therefore, we speculate that with the exception of ovarian CCC, diseases that increase serum TFPI2 level are very rare; however, very few reports have assessed the serum level of TFPI2 is investigated in other kinds of cancer patients." (PMID 27798689, 2016). "Thus, TFPI-2 may be a promising theranostic biomarker for cancer." (PMID 39153052, 2024). "Since TFPI2 has been identified as an early detection marker of CRC, growing evidence has suggested this gene as a potential biomarker in other types of cancer, such as gastric lung, pancreas, oral, esophageal, and liver cancer." (PMID 33946400, 2021). "We identified the transcriptional expression of 9 genes regulated by promoter hypermethylation in OSCC and finally provided 3 genes (TFPI2, SOX17, and GATA4) that were frequently hypermethylated in primary OSCC tumors in a cancer-specific manner." (PMID 31405379, 2019). "We observed interesting relationships among the most methylated genes (TFPI2, SOX17, and GATA4) in OSCC cell lines and primary tumors in a cancer-specific manner." (PMID 31405379, 2019). "We identified that TFPI2, SOX17, and GATA4 are frequently hypermethylated in human OSCC cells in a cancer-specific manner and that the transcriptional expression of these genes is regulated by promoter hypermethylation in OSCC." (PMID 31405379, 2019). "TFPI2 indirectly inhibits the activation of the matrix metalloprotease (MMP), which needs trypsin and plasmin and suppresses cancer invasion." (PMID 29757260, 2018). "p16, TFPI2, the cadherins E-cadherin and CDH13, and the secreted frizzle-related proteins (SFRPs) SFRP1 and SFRP5 were desilenced in cancer cell lines." (PMID 23593653, 2013). "Further studies will be necessary to explore the great therapeutic potential of TFPI-2 in NPC and other cancer." (PMID 21062455, 2010). "By inhibiting plasmin, TFPI-2 effectively decreases the activation of MMP-1, MMP-3 and MMP-9 and reduces the invasive potential of several cancer cell lines." (PMID 21062455, 2010). "Overall, NF-κB activation is common in these cancers, though TFPI2’s role in clear versus non-clear subtypes needs further study." (PMID 40361374, 2025). "Additionally, Tfpi2 reduces ECM proteolysis; thus, its upregulation counteracts ECM degradation by cancer cells and inhibits cell invasion." (PMID 39859313, 2025). "As KLK12 could activate proMMP-1 and -3, inhibition of KLK12 by TFPI-2 might limit MMP activation and inhibit cancer progression." (PMID 39153052, 2024). "TFPI-2 stabilizes the TME, thus limiting the development of cancer." (PMID 39153052, 2024). "Gene expression analysis across all three cancer types subsequently found a common increase in the expression of five genes (BCAR1, COL1A1, IGSF3, RRAD, and TFPI2), which may further inform biomarker study for identifying CTCs." (PMID 36980717, 2023).